CAT (catalase)
Diseases named in the same sentence as CAT in open-access papers (continued):
Sharing a sentence is not in itself a finding about the gene and the disease.
diabetes (continued). "The butyric acid supplementation was shown to markedly increase the activities of serum and renal antioxidant enzymes, including superoxide dismutase, catalase, and glutathione peroxidase, and inhibit lipid peroxidation in rats with STZ-induced diabetes." (PMID 35899118, 2022). "Accordingly, our results revealed that the diabetes mellitus group (untreated diabetic control group) had elevated MDA level and decreased antioxidant enzyme levels (SOD, CAT, GRx, and GST)." (PMID 33661932, 2021). "The role of gliclazide and metformin to increase the antioxidant capacity of erythrocyte CAT, GPX, and glutathione S‐transferase enzyme in treated patients and reduced the OS in diabetes." (PMID 34622023, 2021). "The diabetic mellitus-induced rats followed by treatment with camel milk significantly increased the levels of SOD, CAT and GSH." (PMID 34067516, 2021). "Of the top 15 proteins found by Cytoscape 3.6.1, 8, CAT and OGG1 (downregulated) and CASP3, COMT, CYP1B1, DPYD, NQO1, and PTGS1 (upregulated), were dysregulated in diabetes-related kidney disease." (PMID 34367469, 2021). "Diabetes induction prompted CK-MB, LDH levels in serum, cardiac catalase, and superoxide dismutase activity, as well as cardiac TBARs and carbonylated protein." (PMID 34993484, 2021). "In this study, hUCMSCs reduced the content of malondialdehyde and expression of 4-HNE protein in the kidneys of diabetic rats and increased the content of CAT and GPX of hGMCs, indicating that hUCMSCs can improve oxidative stress in diabetes." (PMID 34380544, 2021). "In diabetes mellitus, high glucose can inactivate antioxidant enzymes SOD, POD, and, CAT by glycating these proteins, thus producing induced oxidative stress, which in turn causes lipid peroxidation." (PMID 33897432, 2021). "The oxidative impact of diabetes on the testicular tissue was evaluated by determining the activity of enzymes such as SOD, GPx, and CAT." (PMID 33187275, 2020). "STZ-induced Diabetes significantly reduced the SOD and CAT activities in rats (F = 10.84, p < 0.05; F = 14.18, p < 0.05)." (PMID 32792939, 2020). "In fact, embelin has been reported to act as an antioxidant by stimulating the synthesis of antioxidant defense systems such as SOD, catalase, GSH in a high fat diet and streptozotocin-induced diabetes in Wistar rats." (PMID 32380755, 2020). "In contrast, induction of diabetes and/or aflatoxin intoxication significantly reduced GSH concentrations and GSH-Px, SOD, and CAT activities in both hepatic and renal tissues in the 3rd, 5th, and 7th groups in comparison to the control rats." (PMID 32104544, 2020). "The present study showed diabetes-induced oxidative damage to the kidneys as evidenced by significant changes in MDA, thiol and renal activities of SOD and catalase." (PMID 32995328, 2020). "Saffron administration brought about an improvement of antioxidant enzymes CAT, SOD and GPx and a decrease in the levels of MDA in streptozotocin-induced diabetes." (PMID 33367177, 2020). "The amount of SOD, CAT, and GSH-Px decreased significantly in the livers of the diabetes mice compared with the blank group (p < 0.01, p < 0.01, and p < 0.05, respectively)." (PMID 31108940, 2019). "Diabetes is accompanied by enhanced production of free radicals and diminished antioxidants including SOD, CAT and glutathione peroxidase (GSHPx)." (PMID 31545909, 2019). "A study by Lortz and Tiedge studied antioxidant activity in diabetes and found that overexpressing SOD and catalase can shield pancreatic islets from ROS and maintain insulin production." (PMID 31510091, 2019). "Diabetes mellitus is known to decrease antioxidant enzymes (especially SOD, CAT and GPx) activities in the body system of such patients." (PMID 31513755, 2019). "Orally administered curcumin in diabetes induced by STZ in rats has been shown to improve the anti-oxidative status by enhancing the levels of superoxide dismutase, catalase, and glutathione peroxidase." (PMID 30818888, 2019).
diabetes (continued). "On the other hand, the inducement of diabetes mellitus led to a significant decrease in antioxidant capacity quantified by TAC and catalase (Mann-Whitney test p < 0.002)." (PMID 30818888, 2019). "Diabetes induced an increase in the SOD and CAT activities and in the level of the lipid peroxidation marker TBARS." (PMID 31771099, 2019). "In diabetes mice, MDA level was increased and activities of antioxidant enzymes (SOD, CAT, and GSH) levels were significantly decreased." (PMID 29853958, 2018). "The increase in free radical generation in STZ induced diabetes has been reported to decrease the activities of hepatic SOD and CAT in experimental rats and hamsters." (PMID 30596093, 2018). "The results of the present study demonstrated that diabetes significantly increased MDA levels and decreased the activities of antioxidants SOD and CAT in both hippocampus and liver." (PMID 30254687, 2018). "This Catalase suppression may be due to Vanadyl sulfate supplementation, as a previous study reported that Vanadyl sulfate administration to diabetic rats significantly decreased serum antioxidant enzyme levels, which were significantly raised by diabetes in muscle tissues." (PMID 32153902, 2018). "In diabetes, high glucose levels can inactivate the antioxidant enzymes SOD, CAT, and GPx via glycation of these proteins, which produces oxidative stress that overcomes the antioxidant defence mechanisms of the body." (PMID 29713363, 2018). "On the contrary, the present investigation revealed an increase in the antioxidant enzymes (CAT and SOD) activities in the kidney, liver, and heart tissue homogenates of STZ induced diabetes." (PMID 30596093, 2018). "While diabetes induces a decrease in catalase activity and TBARS production without any modulation of TAOC, cherry consumption was able to increase catalase activity and TAOC leading to a decrease in TBARS complications." (PMID 30029691, 2018). "After 8 weeks following diabetes induction, the expression of SOD1 was unchanged; however, the catalase expression was higher compared to CT." (PMID 28781721, 2017). "Consistent to this idea, reduced glutathione (GSH) or anti-oxidant enzymes, such as superoxide dismutase (SOD), catalase (CAT), and glutathione peroxidase (GPx), exhibit the ability to ameliorate the pathophysiological problems of diabetes." (PMID 29036927, 2017). "This streptozotocin-induced inhibition in catalase activity and rise in AT1 immunofluorescence in heart tissue from rats with diabetes was considerably reduced by zingerone administration." (PMID 29206854, 2017). "Suppressed levels of peroxisomal biogenesis markers such as PMP70, catalase, and PEX5 in kidneys of STZ-induced diabetes mice were recovered by APX-115 or losartan." (PMID 29088780, 2017). "In addition, myricetin down-regulated the expression of catalase and superoxide dismutase—the two main enzymes involved in the induction of cellular oxidative stress, those play important role in the pathogenesis of type 2 diabetes mellitus and its complications." (PMID 27765936, 2016). "During first month following induction of diabetes in rat, oxidative stress biomarkers (i.e. SOD, GPx, CAT and LPO) increased." (PMID 27471738, 2016). "Our findings of decreased activities of CAT and SOD in persons with diabetes, is in conformity with that of other researchers." (PMID 25922827, 2015). "Diabetes markedly reduced T-GSH, NP-SH, CAT and SOD, while TBARS, TNF-α and IL-1β levels were increased in the diabetic testis compared to non-diabetic controls." (PMID 26122042, 2015). "Together with hydrogen peroxide and catalase, MDA is commonly used as oxidative stress markers in diabetes." (PMID 23855679, 2013). "On the other hand, our results have evidenced that chronic effect of diabetes in brain led to an upregulation of GPx activity, and a downregulation of SOD and CAT activities, as well as a higher lipid peroxidation levels in nondiabetic rats after 90 days." (PMID 24982856, 2013).
diabetes (continued). "Previous studies reported that expression of Nrf2 and antioxidant genes, such as HO-1, SOD, catalase (CAT), and GPx, was increased in diabetes." (PMID 23737649, 2013). "STZ induced diabetes inactivate the activatedantioxidant enzyme such as SOD, CAT, and GPx by fluctuating these proteins thusproducing induced oxidative stress, continuously oxidative stress caused the LPO." (PMID 24349947, 2013). "In this study, significant (P < 0.05) reduction of GSH and antioxidant enzymes (SOD, CAT, and GSH-Px) activity as well as significant (P < 0.05) increased lipid peroxidation reflects oxidative stress of the liver in experimental diabetes." (PMID 22956978, 2012). "In the treatment groups, both Rutin and Naringin in combination with insulin treatment in diabetic rats produced protection from diabetes and improved all the sperm parameters, decreased the MDA levels and increased the SOD and catalase levels." (PMID 24250392, 2011). "In the current study, SOD, CAT and GSH-Px showed lower activities in liver and kidney during diabetes and the results agree well with the earlier published data." (PMID 22191036, 2011). "The present data also show that STZ-induced diabetes disturbs actions of hepatic antioxidant enzymes (SOD, CAT and GPx)." (PMID 20931083, 2010). "In particular, the levels of catalase (CAT), superoxide dismutase (SOD), and glutathione peroxidase (GPx) were significantly reduced in the diabetes group (p < 0.01), which is indicative of enzyme depletion that is generated by oxidative stress." (PMID 40563973, 2025). "In the study of related antioxidant function, PNS increased the expression of superoxide dismutase (SOD), catalase (CAT) and glucose peroxidase (GPx) and decreased the expression of malondialdehyde (MDA) in the serum of diabetes mice, suggesting the antioxidant capacity of PNS." (PMID 40771280, 2025). "Spermidine treatment significantly mitigated these alterations, lowering glucose levels, alleviating histopathological injury, elevating the antioxidant defense (GSH, SOD, CAT, GPx) and the Nrf2 and decreasing MDA and TGF-β concentrations (p < 0.05 vs. Diabetes)." (PMID 41300451, 2025). "Faecalibaculum, Desulfovibrio_R, UBA3282, and Bifidobacterium were negatively correlated with most index components of diabetes, such as blood glucose level, insulin resistance index, and TG, and positively correlated with SOD, GSH-PX, CAT, and other components." (PMID 40525132, 2025). "Additionally, metabolic benefits of the eggplant fruits diet are demonstrated through increased SOD, catalase, and GPX activities which support the notion that reducing oxidative stress is a viable strategy in diabetes management." (PMID 40869081, 2025). "Decreased SOD, GSH and CAT activity in diabetes individuals compared to nondiabetes individuals has been reported." (PMID 41013820, 2025). "It has been reported that SOD and CAT levels are considerably reduced in patients with DR compared to those with diabetes who do not have ocular complications." (PMID 40332476, 2025). "Furthermore, in a rat model of STZ-induced diabetes, GA significantly reduced thiobarbituric acid-reactive substances and lipid hydroperoxides, enhanced activities of superoxide dismutase (SOD), catalase (CAT), and glutathione peroxidase (GPx)." (PMID 39840111, 2024). "On the other hand, the activity of catalase in the heart was not affected by diabetes with or without insulin or sarpogrelate treatment." (PMID 39057635, 2024). "Furthermore, diabetes triggered renal oxidative stress, evidenced by increased Malondialdehyde (MDA) levels and decreased levels of glutathione peroxidase (GPx), catalase, and superoxide dismutase (SOD)." (PMID 38510054, 2024). "Participants with diabetes adhering to a legume-based TLC diet exhibited significant reductions in oxidative stress indicators, with decreased malondialdehyde and oxidized LDL levels and increased nitric oxide and catalase activity." (PMID 38794673, 2024).
diabetes (continued). "Hence, our findings that diabetes resulted in increased pancreatic lipid peroxidation, depleted GSH levels as well as reduced CAT and SOD activities were in line with previous studies." (PMID 39070783, 2024). "This study found diabetes-instigated increased cardiac oxidative stress as evidenced from the increased heart level of the lipid peroxidation indicator-MDA but decreased SOD activity, GPx activity, and CAT activity in the diabetic heart." (PMID 39239455, 2024). "Moreover, MFP can improve diabetes by regulating OS, which is mainly manifested in inhibiting MDA content, and increasing SOD, GPx, and CAT levels." (PMID 37497112, 2023). "In our research, the induction of periodontitis and the diabetes in Wistar rats resulted in increased values of MDA, an indicator of oxidative stress, and decreased values of CAT, an indicator of the antioxidant capacity, measured in the blood of the experimental animals." (PMID 38132422, 2023). "Dietary intake of both flower and banana inflorescence from M. balbisiana Colla reversed deleterious effect of diabetes on blood biochemical markers, since there were decreases in total cholesterol, triglycerides, LDL and MDA, and enhancement on HDL and CAT serum concentrations." (PMID 37655002, 2023). "However, HNCP administration markedly decreased the MDA level and increased the levels of SOD, CAT, and GSH-Px in STZ-induced diabetes mice." (PMID 37888453, 2023). "Diabetes enhances oxidative stress and compromises antioxidant defences, as evidenced by increased superoxide generation and reduced Superoxide dismutase (SOD) activity catalase (CAT) and glutathione (GLT)." (PMID 36766773, 2023). "These discrepancies could be attributed to the longer duration of T2D, diabetes stage, genotype background, different study populations, different sample sizes, and different SOD and CAT analysis methods." (PMID 37432193, 2023). "The activity of CAT was increased in diabetes+IE group, albeit not to the levels in the control group." (PMID 37098926, 2023). "Increased ROS levels in diabetes can lead to decreased production of SOD, GPx, and catalase." (PMID 36771275, 2023). "A disturbed balance between pro-oxidative agents and the body’s antioxidant defense (glutathione-peroxidase (GPd), superoxide-dismutase (SOD) and catalase (CAT)) is considered to be the main factor in the pathogenesis of micro- and macrovascular complications that occur in patients with diabetes." (PMID 36829941, 2023). "However, resveratrol administration at doses of 10 or 20 mg/kg of body mass for 4 weeks in rats suffering from streptozotocin-induced diabetes leads to a reduction of AOPP, as well as the activity of catalase (CAT) and superoxide dismutase (SOD) in the lens." (PMID 35889930, 2022). "In another study, receiving 200 mg/kg/day EEP for 3 weeks in two groups of rats, one group before induction of diabetes and another group after induction of it, showed significant reductions in serum MDA and NO, and significant elevation in serum SOD, CAT, and GST concentrations." (PMID 35057819, 2022). "Furthermore, in a rat model of diabetes, treatment with CM for two months, decreased MDA levels and increased CAT, glutathione reductase (GR) and SOD levels indicating the antioxidant activity of CM." (PMID 35493477, 2022). "Quercetin was able to prevent STZ-induced diabetes and reversed the inhibitory effect of STZ on the activity of antioxidant enzymes such as glutathione peroxidase (GSHPx), superoxide dismutase (SOD), and catalase (CAT) in the pancreas." (PMID 35892731, 2022). "Catalase (CAT) is an intracellular enzyme that dissociates the hydrogen-peroxide (H2O2) to generate H2O and O2 and attenuates the level of reactive oxygen species that complement pathological conditions such as diabetes." (PMID 36387342, 2022). "Diabetes did not alter vascular superoxide dismutase 1, catalase, and glutathione peroxidase mRNA levels." (PMID 36613929, 2022).
diabetes (continued). "In experimentally-induced diabetic animals, infertility is connected with enhanced ROS production and lipid peroxidation in the testes, as well as with disturbance in endogenous antioxidative machinery, including SOD and CAT activities." (PMID 35885378, 2022). "To further investigate the relationship between the GRb1 amelioration on oxidative stress and riboflavin effects, we also treated diabetes larvae with riboflavin and measured the oxidative stress levels of ROS, cell death, MDA and CAT activity in whole larval tissues." (PMID 36355094, 2022). "Diabetes larvae showed a significant increase in ROS, cell death, MDA levels and CAT activity." (PMID 36355094, 2022). "To determine whether PQQ ameliorated diabetes-induced oxidative stress, we measured the activities of MDA, SOD, GSH-px, and CAT in heart tissue." (PMID 34997266, 2022). "Firstly, to determine whether GRb1 may regulate redox status in the diabetes model, we evaluated the influence of GRb1 treatment on ROS production, cell death, MDA levels, and CAT activity changes in diabetes larvae." (PMID 36355094, 2022). "Hence, the aqueous extract of this lichen species increased the activity of the antioxidant enzymes SOD, catalase (CAT), and GPx, and reduced the levels of the lipid peroxidation biomarker MDA in human erythrocytes with type 1 diabetes mellitus." (PMID 35956939, 2022). "We found that sitagliptin protected against diabetes-induced oxidative stress by reducing superoxide, TXNIP, PKC, and DNA/RNA/protein oxidative damage, and it prevented the downregulation of NRF2 and antioxidant enzymes, with the exception of catalase." (PMID 35883908, 2022). "STZ-induced diabetes mellitus significantly reduced the mean antioxidant enzyme levels such as malondialdehyde((MDA), glutathione transferase (GST), superoxide dismutase (SOD), and catalase (CAT)." (PMID 36556476, 2022). "Therefore, this study compared the serum GPER-1 levels and oxidative stress markers(malondialdehyde [MDA], catalase [CAT], and superoxide dismutase [SOD]) in patientswith diabetes and healthy individuals." (PMID 35857982, 2022). "In the course of diabetes, there was a significant (p<0.05) reduction in SOD and CAT activities." (PMID 32569454, 2021). "T2DM: type 2 diabetes mellitus; SGLT2i: sodium-glucose cotransporter 2 inhibitors; SOD: superoxide dismutase; MnSOD: manganese superoxide dismutase; TAC: total antioxidant capacity; R-SH: sulfhydryl groups; CAT: catalase; n: number of patients." (PMID 34336104, 2021). "The total sum of squares explained the variations of MDA, GSH, GSSG, GSH/GSSG and CAT due to the changes in treatment from the control group to those with diabetes mellitus and periodontitis who were not treated with curcumin, rutin or a combination of both." (PMID 33801378, 2021). "Additionally, decreased activity of SOD and CAT, reduced GSH concentration, and increased MDA level have been suggested to be responsible for oxidative damage and apoptosis in TAC-induced diabetes mellitus in an animal model." (PMID 33679236, 2021). "Additionally, it has been demonstrated that C. sativus aqueous extract (10, 20, and 40 mg/kg) mitigated MDA and nitric oxide levels, while it appended the levels of GSH and catalase and SOD activities following streptozotocin-induced diabetes in rats." (PMID 34956439, 2021). "Nevertheless, in our experiment, catalase gene expression was not affected by diabetes or by crocin administration." (PMID 32161725, 2020). "The activities of these enzymes, however, are typically disrupted in the context of diabetes, with significantly increased SOD, GSH-Px, and CAT activity and significantly reduced MDA activity being evident in the cardiac tissue of diabetic mice relative to healthy WT controls." (PMID 33061882, 2020). "The effect of diabetes on catalase gene expression in the liver is an element not thoroughly studied and the few existent works have no consistent results." (PMID 32161725, 2020).